IGFBP3 (insulin like growth factor binding protein 3)
Diseases named in the same sentence as IGFBP3 in open-access papers (continued):
Sharing a sentence is not in itself a finding about the gene and the disease.
steatosis (5 papers, 2013 to 2024). Increased lipid within the cytoplasm of cells. "In patients with advanced liver injury, caused by hepatitis C infection or steatosis, serum levels of IGFBP3 are increased which could be an indication of HSC activation." (PMID 24358328, 2013). "Serum IGFBP-3 is decreased in patients with NAFLD, whereas the IGF-1/IGFBP-3 ratio has been associated with a lower likelihood of NAFLD, lower-grade steatosis, and histopathologic features of the liver biopsy, including ballooning and inflammation." (PMID 38541155, 2024). "IGF1/IGFBP3 ratio revealed a tendency to decrease in patients with steatosis, confirmed by ultrasound and increased aminotransferases, as well as the ones with NAFLD and portal fibrosis." (PMID 29702590, 2018). "Children with NASH showed significantly lower levels of IGF-1 SDS (−1.3 vs. 1.0, p < 0.05) and IGF-1/IGFBP-3 ratio (0.086 vs. 0.14, p < 0.02) and higher grades of steatosis (2.64 vs. 1.84, p < 0.001), lobular inflammation (1.64 vs. 1.14, p = 0.002), and ballooning (1.79 vs. 0.44, p < 0.001)." (PMID 36831184, 2023). "Additionally, hepatic stellate cell-derived IGFBP3 increases lipogenesis via integrin receptor/Src-kinase signaling and p-Akt up-regulation in primary hepatocytes, thereby contributing to ethanol-induced steatosis." (PMID 36582223, 2022). "However, contrasting results were observed in other studies, which showed that increased expression of IGFBP3 in patients with alcoholic hepatitis could directly promote lipid droplet formation facilitating ethanol-induced steatosis." (PMID 36582223, 2022). "IGFBP3 levels were higher in NAFLD patients, as well as in cases of advanced steatosis in biopsy-confirmed NAFLD." (PMID 29702590, 2018).
benign breast disease (4 papers, 2007 to 2025). "In summary, we demonstrated that circulating levels of serum IGF-I and IGFBP-3 are associated with TDLU count among women with benign breast disease, and that the strongest associations are found among women who have high mammographic density." (PMID 26893016, 2016). "Similarly, we hypothesize that higher serum levels of IGF-I and the IGF-I:IGFBP-3 ratio are associated with lower levels of TDLU involution among women with benign breast disease." (PMID 26893016, 2016). "Among patients with benign breast disease, IGFBP3 expression in the tumor was significantly higher than that in their adjacent normal tissue." (PMID 17210081, 2007). "Most previous studies have focused on evaluating circulating IGFBP-3, and almost none have systematically investigated the level of this important protein in breast tissues from patients with invasive cancer and benign breast diseases (BBDs)." (PMID 17210081, 2007).
Cachexia (4 papers, 2021 to 2025). Severe weight loss, wasting of muscle, loss of appetite, and general debility related to a chronic disease. "For a biomarker to be responsive to change, it must be related to the mechanism of action of the intervention and/or the underlying cachexia process that is modified by the intervention, as seen with IGFBP‐3, IGF‐1 and anamorelin." (PMID 38783477, 2024). "All these data suggest that during inflammation, the decrease in serum and muscle IGF-1, together with the increase in muscle IGFBP-3, are associated with the increase in muscle proteolysis and cachexia." (PMID 34502376, 2021). "Patients with lower vs. higher IGF-I levels were older, had a similar BMI and frequency of wasting syndrome with unintentional weight loss, higher LV mass at baseline and GHBP levels, lower IGFBP3 and IGF-I/GH ratio, and similar levels of GH." (PMID 38587563, 2025). "An increase in muscle IGFBP-3 has also been observed in cachexia induced by experimental models of arthritis and cancer." (PMID 35408999, 2022). "Patients with vs. without wasting syndrome with unintentional weight loss had higher GH and GHBP, lower log IGF-I/GH ratio, and similar levels of IGF-I and IGFBP3." (PMID 38587563, 2025).
central precocious puberty (4 papers, 2018 to 2025). "Since members of the IGF family are involved in the onset of puberty, we aimed to identify polymorphisms in insulin (INS), IGF-1, IGF-2, IGF-1 receptor (IGF1R), IGR2R, and IGF binding protein 3 (IGFBP-3) that may alter the risk for development of central precocious puberty." (PMID 30249230, 2018). "Patients with hCG-induced precocious puberty would have age-matched IGF-1 or IGFBP-3 levels after regression of precocious puberty." (PMID 36425849, 2022). "IGF-1 and IGFBP-3 levels in patients with hCG-induced precocious puberty were analysed and compared during the therapy for hCG-secreting tumors." (PMID 36425849, 2022). "Furthermore, IGF-1 and IGFBP-3 levels in children with precocious puberty were significantly higher than those in normal children of the same age and sex." (PMID 38356806, 2024). "In children with hCG-induced precocious puberty, IGF-1 or IGFBP-3 levels present a heterogeneity and commonly vary within an age-matched reference." (PMID 36425849, 2022).
cutaneous melanoma (4 papers, 2010 to 2025). A primary melanoma arising from atypical melanocytes in the skin. "In the present work, we have evaluated the levels of IGFBP-3 in the blood serum and tissues of patients affected by cutaneous melanoma, showing that loss of IGFBP-3 from both is strongly correlated with disease progression and reduced survival." (PMID 24905466, 2014). "IGFBP3 was more strongly expressed in metastatic and cutaneous melanoma compared to melanocytes." (PMID 20663135, 2010).
heart failure (4 papers, 2019 to 2025). Inability of the heart to pump blood at an adequate rate to meet tissue metabolic requirements. "In the age-, sex-, and community-matched model, higher serum concentrations of IGF-II and IGFBP3 tended to be inversely associated with mortality from heart failure in both quartile and continuous analyses." (PMID 30078811, 2019). "Several biomarkers—including IGFBP-1, IGFBP-2, IGFBP-3, FGF-23, MMP-2, MMP-7, TIMP-2, and RAGE/AGE—were significantly elevated in patients with cardiac involvement and independently associated with either heart failure decompensation or death/transplantation." (PMID 41226753, 2025). "Therefore, within participants of the Japan Collaborative Cohort study (JACC), we investigated the associations of serum concentrations of IGF-I, IGF-II, IGFBP3, and TGF-β1 with mortality from heart failure in a nested case-control study." (PMID 30078811, 2019). "In heart failure cases and age-, sex-, community-, and year of blood withdrawal-matched controls, we measured serum concentrations of IGF-I, IGF-II, and IGF binding protein 3 (IGFBP3) and transforming growth factor (TGF-β1)." (PMID 30078811, 2019).
invasive breast carcinoma (4 papers, 2005 to 2020). A carcinoma that infiltrates the breast parenchyma. "Strong (2+) IGFBP-3 expression was seen in 32 invasive breast cancers and 40 cases of DCIS." (PMID 15642160, 2005).
kidney cancer (4 papers, 2010 to 2024). Primary or metastatic malignant neoplasm involving the kidney. "We conducted a case–cohort study nested within the Alpha-Tocopherol, Beta-Carotene Cancer Prevention (ATBC) study of Finnish male smokers to examine the prospective relation of IGF-I and IGFBP-3 to risk of kidney cancer." (PMID 20517306, 2010). "IGFBP3 expression remained a marker of both kidney cancer and liver TECs, however, IGFBP5 expression was mainly seen in the kidney and not in liver NECs." (PMID 39516665, 2024). "Low serum IGF-I levels in this cohort of older middle-aged male smokers are associated with increased kidney cancer risk, independent of IGFBP-3." (PMID 20517306, 2010). "In this cohort of Finnish male smokers, we found a significant inverse association between serum IGF-I concentrations and risk of kidney cancer and a nonstatistically significant positive association for IGFBP-3." (PMID 20517306, 2010). "For IGF-I/IGFBP-3 molar ratio, overall the association between molar ratio and kidney cancer was not statistically significant (Type III Analysis of Effects, P=0.39), nor were any of the individual quartiles when compared with the reference category." (PMID 20517306, 2010).
liver disease (4 papers, 2019 to 2024). "In LCH patients admitted to hospital due to complications of the disease, IGF-I and IGFBP-3 serum levels were associated with variables related to liver dysfunction and with more advanced liver disease." (PMID 35251204, 2022). "Despite the fact that transcriptional analysis of liver IGFALS to examine its role in liver diseases is rarely performed, IGFALS forms ternary complexes with IGF-I and IGFBP3 in the circulation and regulates body growth, development, and other physiological/pathophysiological processes." (PMID 36582223, 2022).
liver dysfunction (4 papers, 2014 to 2022). "The estimation of serum IGF1, IGF2 and IGFBP3, together with Child-Pugh score, is more effective in predicting liver dysfunction and its severity, compared to Child-Pugh score alone." (PMID 25225571, 2014). "GH resistance is an increasingly recognized feature related to the reduction of IGF-I, IGF-II, and IGFBP-3 in liver dysfunction that may have been further pathogenically affected by the severity of liver dysfunction, the disorder of portosystemic shunting, and malnutrition of hepatic storage." (PMID 33240216, 2020). "However, in patients with cirrhosis, despite the increase in circulating GH levels, serum IGF1, IGFBP3 and ALS levels and the IGF1 response to GH were found to be lower than in controls, resembling a condition of GH resistance, as a consequence of liver dysfunction." (PMID 25225571, 2014).
lung adenocarcinoma (4 papers, 2021 to 2022). A carcinoma that arises from the lung and is characterized by the presence of malignant glandular epithelial cells. "For the third pair of networks, it was demonstrated that the testis-specific protein Y-linked 1 (TSPY1) activates the PI3K/AKT and RAS signaling pathways by suppressing IGFBP3 expression in lung adenocarcinoma and liver hepatocellular carcinoma progression." (PMID 35529499, 2022).
meningioma (4 papers, 2007 to 2023). A generally slow growing tumor attached to the dura mater. "Previous studies already reported an upregulation of IGFBP-3 in atypical and anaplastic meningiomas." (PMID 33096816, 2020). "In summary, the results of our study suggest possible roles of VEGF, PlGF, and IGFBP-3 during tumorigenesis and/or tumor behavior in grade I meningiomas." (PMID 33096816, 2020). "In the present study, FTV were found in almost 50% of grade I meningiomas and were strongly associated with VD, increased expression of VEGF, PlGF, and IGFBP-3, and a 2-fold increased risk of tumor recurrence." (PMID 33096816, 2020). "Aside from allowing identification of individuals with increased risk of recurrence after surgery for grade I meningiomas, our data also present potential promising targets (e.g., VEGF, PlGF, and IGFBP-3) for adjuvant antiangiogenic therapy in these patients." (PMID 33096816, 2020). "In summary, the occurrence of fibrotic tumor vessels in grade I meningiomas is strongly associated with vessel density, disruption of the arachnoid layer, expression of VEGF, PlGF, IGFBP-3 and tumor recurrence." (PMID 33096816, 2020). "In addition, we found induction of IGFBP3, CENPF, CKS2 and reduction of LTBP2, PTPRF in high-grade meningiomas as previously reported." (PMID 17937814, 2007). "While patients with refractory meningiomas showed a good response to therapy with a VEGF inhibitor in a phase II trial, an IGFBP-3 inhibitor has not yet been administered for intracranial tumors." (PMID 33096816, 2020).
neuroblastoma (4 papers, 2021 to 2025). Neuroblastoma (NB) is the most common solid, extracranial childhood tumor. "In vitro functional studies using SH-SY5Y neuroblastoma cells demonstrated that IGFBP3 significantly attenuated cytotoxicity and apoptosis induced by the neurotoxin MPP+." (PMID 41278191, 2025). "DNA microarray analysis of Aβ treated neuroblastoma cells explore the upregulation of the insulin-like growth factor binding proteins 3 and 5 (IGFBP3/5)." (PMID 34572312, 2021).
osteoarthritis (4 papers, 2012 to 2024). A noninflammatory degenerative joint disease occurring chiefly in older persons, characterized by degeneration of the articular cartilage, hypertrophy of bone at the margins and changes in the synovial membrane. "Further analysis of these enriched pathways in injurious hydrostatic pressure highlighted differential expression of several genes known to be involved in osteoarthritis, such as Fgf2, Ep300, Ngf, Adam9, Igfbp3, Sox9, Comp, Col6a1, Col6a2 and Col11a1." (PMID 38144567, 2023). "In addition, several genes known to play a key role in progression of osteoarthritis (e.g., Fgf2, Ep300, Ngf, Adam9, Igfbp3, Sox9, Comp, Col6a1, Col6a2 and Col11a1) were modulated in our injurious hydrostatic pressure hip cap datasets, thereby validating this approach." (PMID 38144567, 2023). "During osteoarthritis (OA), the anabolic responses of chondrocytes to IGF-I are likely to be prevented by the enhanced production of IGF-binding proteins (IGFBPs), especially IGFBP-3." (PMID 23036517, 2012).
pituitary adenomas (4 papers, 2008 to 2021). "The other genes including POU1F1, IGFBP3, and CCNB1 were also reported to correlate with pituitary adenomas." (PMID 25642247, 2015).
prostatic intraepithelial neoplasia (4 papers, 2004 to 2019). "Tennant and colleagues compared the expression of IGFBP-3 in prostate tissue containing benign epithelium, high-grade prostate intraepithelial neoplasia (PIN), and adenocarcinoma." (PMID 17210081, 2007). "A small study of 58 men with high-grade prostatic intraepithelial neoplasia taking lycopene (30 mg/day) over the same period (6 months) as this study, found no changes in serum IGF-I (P = 0.99) and IGFBP-3 (P = 0.53) levels between pretreatment and post-treatment groups." (PMID 30921005, 2019).
pterygium (4 papers, 2009 to 2022). A wedge-shaped fibrovascular lesion arising from the bulbar conjunctiva and extending to the cornea. "Among the top 20 connective genes from PPI network, FN1, VWF, and IGFBP3 have been reported and expressed disorderly in pterygium." (PMID 31341891, 2019). "Our results show that protein expression levels for keratin 6, CEACAM5, CD24, MSMB and MUC5AC were increased, whereas NR4A2 and IGFBP3 were reduced in pterygium, consistent with the transcript changes detected by the microarray analysis." (PMID 19272163, 2009). "FN1 was involved in cell adhesion and migration processes, which has been found to enhance the EMT in pterygium, and IGFBP3 could control cell proliferation." (PMID 31341891, 2019). "IGFBP3, present in un-involved conjunctival stroma and epithelium, and NR4A2, present in conjunctival epithelium, were reduced in pterygium." (PMID 19272163, 2009). "The low level of IGFBP3 (insulin-like growth factor binding protein 3) in pterygium suggests that growth proliferation is not controlled analogous to tumor cells." (PMID 33540506, 2021).
renal carcinoma (4 papers, 2009 to 2024). A carcinoma arising from the epithelium of the renal parenchyma or the renal pelvis. "In summary, the results from this study suggest that genetic polymorphisms and haplotypes within the CASP1, CASP5, EGFR, and IGFBP3 genes are associated with renal cancer risk." (PMID 19603096, 2009). "There is strong evidence supporting the biological relevance of genetic variants in EGFR and IGFBP3 and renal cancer risk." (PMID 19603096, 2009). "We identified both haplotypes and SNPs in CASP1/5/4/12, EGFR, and IGFBP3 that were statistically significantly associated with risk of renal cancer." (PMID 19603096, 2009). "In conclusion, our evaluation has identified common genetic variants in CASP1, CASP5, EGFR, and IGFBP3 that could be associated with renal cancer risk." (PMID 19603096, 2009). "Aberrant DNA methylation has been shown to play an important role in the silencing of IGFBP3 expression in several human cancers, including gastric, colorectal, breast, ovarian, and renal cancer, as well as HCC in adults." (PMID 22401581, 2012). "IGFBP3 variation has been evaluated with several other cancer sites, but this is the first study to evaluate SNPs in relation to renal cancer." (PMID 19603096, 2009). "Three regions containing genes associated with renal cancer were identified: caspase 1/5/4/12(CASP 1/5/4/12), epidermal growth factor receptor (EGFR), and insulin-like growth factor binding protein-3 (IGFBP3)." (PMID 19603096, 2009). "In relation to renal cancer, experimental studies have demonstrated that IGFBP3 expression is increased among both clear cell renal tumors and renal cancer cell lines." (PMID 19603096, 2009). "Because IGFBP3 was overexpressed in renal cancers and identified as a driving force for other tumours, the next question was how IGFBP3 functions in ccRCC and whether it is the target of CVB therapy." (PMID 34512163, 2021). "Furthermore, CVB inhibited the invasion and migration of renal carcinoma cells by interfering with the EMT through the suppression of the IGFBP3-AKT/MAPK/STAT3-Snail signalling pathway." (PMID 34512163, 2021). "In addition, with a haplotype-based sliding window method, we identified the same genes with regions that were associated with renal cancer risk at a FDR level <10%: CASP1/5/4/12, EGFR, IGFBP3, and VCAM1." (PMID 19603096, 2009).
rheumatoid arthritis (4 papers, 2022 to 2024). A chronic, systemic autoimmune disorder characterized by inflammation in the synovial membranes and articular surfaces. "IGFBP3 encodes insulin-like growth factor binding protein 3 that has been shown to play a role both in the inflammatory processes and bone destruction observed in rheumatoid arthritis, and is considered a therapeutic agent candidate for treatment of this autoimmune and inflammatory disease." (PMID 35110524, 2022). "In particular, the IGFBP-3 level is reportedly linked to the disease activity of rheumatoid arthritis (RA), consistent with our previous study." (PMID 35382860, 2022). "In one study, comparison of serum in clinically active rheumatoid arthritis (RA) patients and 51 control subjects showed elevated Igfbp3 in RA patients." (PMID 39769264, 2024). "Additionally, IGFBP-3 is involved in inflammatory processes such as rheumatoid arthritis (RA)." (PMID 37834128, 2023).
squamous cell carcinoma (4 papers, 2018 to 2024). A carcinoma arising from squamous epithelial cells. "In contrast, Igfbp3 KO mice with NQO administration showed significantly increased numbers, volume, and burden of tumor nodules with SOX2 expression, a marker of squamous cell carcinoma." (PMID 33801272, 2021).
adult respiratory distress syndrome (3 papers, 2012 to 2022). "The lower circulating levels of IGF1 and IGFBP3 were also associated with the incidence and mortality of adult respiratory distress syndrome (ARDS)." (PMID 35958562, 2022). "Recently, in adults with acute respiratory distress syndrome (ARDS), lower levels of circulating IGF-I and IGFBP-3 were independently associated with ARDS and with mortality." (PMID 22924869, 2012). "Additionally, we found IGFBP3 was specifically downregulated in cells expressing NSP12, a protein with levels that correlate with adult respiratory distress syndrome severity." (PMID 35337019, 2022).
alcohol (3 papers, 2010 to 2025). "Moreover, dependent inhibition of NRP1 targeted HSCs and ameliorated alcohol-induced steatohepatitis by decreasing hepatic lipid droplets as well as inflammation through regulation of the IGFBP3 and SERPINA1A12 signaling pathways." (PMID 36077090, 2022).
Arthritis (3 papers, 2014 to 2023). Inflammation of a joint. "In chronic inflammation induced by arthritis we have found that IGFBP3 expression is also increased in the gastrocnemius muscle but not in the liver." (PMID 25294954, 2014). "In dogs with arthritis, active forms of C1r and C1s, along with reduced concentrations of IGFBP-5, IGFBP-3 and IGF-1, were present in their synovial fluid." (PMID 38002958, 2023).